APOB (apolipoprotein B)
Diseases named in the same sentence as APOB in open-access papers (continued):
Sharing a sentence is not in itself a finding about the gene and the disease.
cardiovascular disease (continued). "We investigated the utilization of apolipoprotein B (ApoB), an independent risk factor for cardiovascular disease, and developed and validated a translational equation for calculating low-density lipoprotein cholesterol (LDL-C) in the Korean population visiting local clinics and hospitals." (PMID 37375689, 2023). "Recent literatures supported the hypothesis that reducing apoB levels led to a decrease in risk of cardiovascular diseases." (PMID 37559117, 2023). "Observing these lipidic alterations in Brazilian women is important since higher levels of LDL and ApoB have been correlated with a higher risk of cardiovascular disease, which, along with the loss of endothelial protection promoted by estrogens, can harm women's health." (PMID 36474222, 2022). "The ApoB/ApoA1 ratio is a strong and new risk factor for cardiovascular disease (CVD)." (PMID 34996506, 2022). "Lipid-driven cardiovascular disease (CVD) risk is caused by atherogenic apolipoprotein B (apoB) particles containing low-density lipoprotein cholesterol (LDL-C), triglycerides and lipoprotein(a) [Lp(a)] and resembles a large and modifiable proportion of the total CVD risk." (PMID 34279797, 2022). "The ratio of ApoB/A1 is a well-studied risk factor for cardiovascular disease." (PMID 35295919, 2022). "Apolipoprotein B is a marker of cardiovascular disease risk and a key molecule in lipid metabolism." (PMID 36470666, 2022). "An unbalanced lipid profile with high total cholesterol (TC), low-density lipoprotein-cholesterol (LDL-C), triglycerides (TG), and low high-density lipoprotein-cholesterol (HDL-C), apolipoprotein A1(Apo-A1), apolipoprotein B (Apo-B) is an established risk factor of cardiovascular diseases." (PMID 29678178, 2018). "Low serum apolipoprotein (Apo) A1 concentrations and high serum ApoB concentrations may be better markers of the risk of cardiovascular disease than high-density lipoprotein (HDL) and low-density lipoprotein (LDL)." (PMID 28264492, 2017). "The apoB/apoA1 ratio is also a marker of risk for future cardiovascular disease." (PMID 29017497, 2017). "Measurement and calculation of the apolipoprotein B (apoB) and apoB/apoA-I ratio may improve the prediction of risk for cardiovascular disease, as it represents the balance between proatherogenic and antiatherogenic lipoproteins." (PMID 23028747, 2012). "Apolipoproteins have been demonstrated to play physiological roles on nutrition transport and energy metabolism, and numerous variants have been revealed in some apolipoproteins including ApoA1, ApoA5, ApoB, ApoC3 and ApoE, which are associated with the risk of cardiovascular disease." (PMID 21799896, 2011). "Our study revealed that BMI might affect a wide range of health-related attributes and also highlights notable sex differences in its impact, including opposite associations for certain attributes, such as ApoB; and stronger effects in men, such as for cardiovascular diseases." (PMID 40498079, 2025). "Furthermore, elevated LDLapoB/LDL‐c ratio have been reported to associate with increased cardiovascular mortality in patients referred for coronary angiography, and levels of apoB are increasingly recognized as the strongest risk markers for cardiovascular disease." (PMID 40129271, 2025). "A higher atherogenic lipid load (as measured by the concentration of total cholesterol, LDL, or apolipoprotein B; or the ratio of total cholesterol to high-density lipoprotein or apolipoprotein B toapolipoprotein A1) is associated with a gradual increase in the incidence of cardiovascular disease." (PMID 35056760, 2022). "Multiple adverse health outcomes have been linked to low apoA1 levels, high apoB levels and high apoB/apoA1 ratios, leading to interest in developing strategies to manage abnormal apo variables for the prevention or treatment of associated metabolic and cardiovascular diseases." (PMID 29312456, 2018).
cardiovascular disease (continued). "Although the concentrations of apoB and apoA-I are associated with cardiovascular disease more strongly than the corresponding lipoprotein cholesterol fractions, the discriminant value of these apoproteins in absolute terms appears to be less than that of their ratio (the apoB/apoA-I ratio)." (PMID 25852220, 2015). "Their Lp(a) and ApoB levels were slightly above the upper limits of normal (38 ± 34 and 112 ± 24 mg/dL), while the ApoA1 levels were with in normal limits (166 ± 28 mg/dL), attesting to a normal lipoprotein metabolism, with an average cardiovascular disease risk." (PMID 20659335, 2010). "Studies indicate that the secretion of atherogenic lipoproteins is highly dependent on APOB levels and elevated level of this protein is correlated with increase incidences of cardiovascular disorders." (PMID 40892857, 2025). "This meta-analysis further evaluated stronger predictors of cardiovascular disease risk—lipid ratios (LDL–HDL, TG-HDL, and ApoB-ApoA1)." (PMID 40935153, 2025). "Oxidised apolipoproteins, especially ApoB and ApoA‐I, have been extensively investigated for their possible role in cardiovascular disease, but much less is known about the oxidation status of other apolipoproteins, and their association with MASLD." (PMID 39822152, 2025). "In our study, essential oil supplementation to drinking water reduced APOB gene expression in the liver, and it is thought that essential oil intake will reduce cardiovascular diseases by lowering cholesterol in cholesterol‐related diseases." (PMID 40028755, 2025). "Studies have shown that genetic proxied total blood phytosterol affects the development of cardiovascular disease through non‐HDL‐c and apolipoprotein B mediation, which makes phytosterol an underlying risk factor for frailty." (PMID 40661798, 2025). "Prior research has demonstrated that the APOB/APOA1 is a risk factor for cardiovascular disease and is associated with an unfavorable prognosis for cardiovascular disease." (PMID 40787622, 2025). "The ApoB/ApoA1 ratio has been identified as associated with T2DM independently, particularly in patients with cardiovascular disease, potentially serving as a predictor of cardiovascular risk in these cases." (PMID 38393015, 2024). "The population of apoB-specific Tregs appears to be diminished in the peripheral blood of patients with cardiovascular disease compared to healthy controls." (PMID 39161593, 2024). "They identified apolipoprotein B, CD14, and pro-basic platelet protein as proteomic markers associated with an increased incidence of cardiovascular disease in women compared to men." (PMID 39336514, 2024). "Apolipoprotein B (ApoB) is increasingly considered a more potent predictor of cardiovascular disease (CVD)." (PMID 38789961, 2024). "There was an independent and direct association between SAA concentrations (>9.4mg/dL) and age, BMIz, apolipoprotein B, and CIMT, suggesting a risk for cardiovascular disease." (PMID 37341220, 2023). "Li and Schooling reported that the T allele of the rs8176746 T/G is associated with lower plasma levels of ApoB and LDL-C, but with a risk of developing some cardiovascular diseases." (PMID 37334748, 2023). "The WDP was associated with higher zBMI and %BF values and increased cardiovascular disease risk markers (LDL/HDL and LDL/ApoB), independently of %BF and zBMI." (PMID 36678200, 2023). "Previous in vivo and in vitro studies have indicated that apoB contributes to the development of DR and cardiovascular diseases." (PMID 35937834, 2022). "Recently, studies have begun to reduce apolipoprotein B as an emerging therapy to prevent cardiovascular disease." (PMID 36470666, 2022). "Further, the ratio of ApoB/A1, which is a strong predictor of cardiovascular diseases, significantly decreased in all experimental groups compared with the vehicle group (p < 0.001)." (PMID 35207485, 2022).
cardiovascular disease (continued). "High levels of apoB correspond to high levels of LDL and VLDL cholesterol, which are often related to a higher risk of cardiovascular diseases." (PMID 36551995, 2022). "Since it was shown that oxLDL is able to enhance NET stimulation, we wanted to investigate and compare the association of circulating oxPL/apoB and NET components in patients with distinct types of cardiovascular disease." (PMID 35203427, 2022). "Apolipoprotein B is a better predictor of cardiovascular diseases than, for instance, LDL cholesterol." (PMID 34127697, 2021). "At the present time, the substitution of apoB for LDL-C in cardiovascular disease prevention guidelines has been deemed unjustified, but discussions continue." (PMID 34677405, 2021). "The increase in the ApoB level in the PPT group indicates that PPT is closely related to the onset of cardiovascular diseases and metabolic diseases." (PMID 33967959, 2021). "Resveratrol treatment after 6 months decreased LDL-c, ApoB, oxLDL, and oxLDL/ApoB on statin-treated patients in primary cardiovascular disease prevention." (PMID 34234682, 2021). "Apolipoprotein B plays an essential role in systemic lipid metabolism, and it is closely related to cardiovascular diseases." (PMID 34305631, 2021). "When the concentrations of apolipoprotein B and LDL cholesterol are discordant in individuals, apolipoprotein B has a stronger association with risk of cardiovascular disease (CVD) than LDL cholesterol." (PMID 32203549, 2020). "The apolipoprotein B/apolipoprotein A1 (ApoB/ApoA1) ratio is recognized as a clinical indicator of cardiovascular disease and ischemic cerebral disease." (PMID 32017458, 2020). "As such, the apoB/apoA-1 -ratio appears to be a better marker for cardiovascular diseases than traditional lipids or lipid ratios." (PMID 28837598, 2017). "Although a number of factors are causally linked to cardiovascular disease (CVD), alterations in lipid metabolism, and specifically an elevated concentration of apolipoprotein B (apoB)-containing lipoproteins are considered major risk factors." (PMID 28984822, 2017). "There is a growing body of evidence indicating that apoB/apoA-1 is a powerful biomarker of future cardiovascular disease as it impacts lipid metabolism, and is a marker of inflammation possessing both anti-oxidant and anti-inflammatory effects." (PMID 28810853, 2017). "Apolipoprotein B (apoB) is known to be a more powerful predictor of cardiovascular disease than conventional lipids." (PMID 28830468, 2017). "Here the authors show that the RBP vigilin regulates translation of mRNA encoding for proatherogenic proteins—apoB, apoC-III and fibronectin—representing a potential therapeutic target in cardiovascular diseases." (PMID 27665711, 2016). "Multiple clinical and epidemiological studies have confirmed that the apoB/apoA-I ratio is a superior marker for cardiovascular disease compared with lipids and lipoproteins or their ratios." (PMID 25852220, 2015). "The blood levels of apoA-I and apoB in patients with cardiovascular disease have been shown to be better discriminators than high-density lipoprotein cholesterol (HDL-C) and LDL-C levels." (PMID 25852220, 2015). "The apoB/apoA-I ratio is increasingly recognized as a better predictor of cardiovascular disease than other traditional cholesterol measures." (PMID 24820970, 2014). "We also found that smoking was associated with unfavorable changes in the levels of apoA1 and apoB and in estimated HDL and LDL particle size, thereby providing a new pathophysiological mechanism linking smoking to increased risk of cardiovascular disease." (PMID 24228807, 2013).
cardiovascular disease (continued). "Apolipoprotein B (Apo B) reflects the total mass of atherogenic particles (VLDL, Intermediate density lipoprotein (IDL), and LDL) and is associated with cardiovascular disease (CVD) independently of LDL-chol levels." (PMID 22114593, 2011). "Apolipoprotein B and LDL cholesterol are causal predictors of cardiovascular disease in adults and may indicate lifetime risk from birth." (PMID 40143821, 2025). "According to the results obtained in our study, increasing the intake of essential oils with food decreased APOB gene expression in the liver, and it is thought that essential oils intake in cholesterol‐related diseases in humans will reduce cholesterol and cardiovascular diseases." (PMID 40028755, 2025). "The evidence suggests that the ApoB/ApoA1 ratio may provide a more accurate assessment of cardiovascular disease risks." (PMID 41245272, 2025). "Lp(a) is an LDL-like particle formed by the interaction of apolipoprotein(a) and apoB-100, and is associated with cardiovascular disease independent of LDL-C or apoB." (PMID 40943485, 2025). "Some studies have confirmed the general risk prediction value of APOB/APOA1 in global populations and the superiority of APOB/APOA1 over HDL or LDL assays alone for early risk identification, which provides strong support for early risk identification in cardiovascular disease." (PMID 40787622, 2025). "In addition, previous studieshave mostly ignored the effect of serum apolipoprotein B (ApoB) on bone health.Serum ApoB is considered to be a key indicator of cardiovascular diseases such asatherosclerosis." (PMID 40475729, 2025). "They exert their effect by competitively inhibiting HMG-CR, leading to reductions in serum total cholesterol, low-density lipoprotein (LDL) cholesterol, apolipoprotein-B (Apo-B), and triglycerides, thereby aiding in the prevention of cardiovascular disease (CVD)." (PMID 38396837, 2024). "Another key protein relevant to cardiovascular disease is APOB." (PMID 38307861, 2024). "Previous studies conducted on Korean populations have used different analytical platforms and primarily focused on risk assessments for cardiovascular disease rather than establishing reference intervals for ApoB." (PMID 37892015, 2023). "Although there is a significant correlation between the level of apolipoprotein A1 and PAGln, the ratio of apolipoprotein A1 and apolipoprotein B is usually used as a marker in clinical practice for the diagnosis of cardiovascular disease, with a threshold of 1.0." (PMID 36797695, 2023). "This discordancemay reflect higher concentrations of remnant cholesterol, which could lead to anatherosclerotic cardiovascular disease beyond apolipoprotein B and thesignificant amounts of atherogenic LDL particulates that interact with thecoronary artery." (PMID 39076405, 2023). "Combinations of LDL-C, non-HDL-C, TRL-C, and ApoB concentrations must be evaluated as the utmost predictive risk marker for development of cardiovascular disease and are recommended in the current guidelines." (PMID 37432317, 2023). "The INTERHEART study have shown that the risk of cardiovascular disease was lower when serum level of apoB was less than non-HDL-C (cholesterol-rich in ApoB particles)." (PMID 35928899, 2022). "The reliability of LDL-C as a short-term endpoint for a long-term disease such as cardiovascular disease lacks utility for clinicians when compared to other endpoints such as serum lipoprotein(a) and apolipoprotein B, or plaque regression endpoints such as atheroma volume reductions." (PMID 36554779, 2022). "Some differences exist between the formation of atherosclerotic plaque, that is, lipid deposition in the walls of systemic arteries in cardiovascular diseases, and esterified lipid-rich deposition and apolipoprotein B lipid deposition in the RPE–Bruch’s membrane in AMD." (PMID 36278032, 2022). "Compared with LDL-C, apoB level has been shown to be a better indicator for cardiovascular disease." (PMID 35928899, 2022).
cardiovascular disease (continued). "Fasting and postprandial concentrations of LDL-C, non-HDL-C, and ApoB are established risk factors for cardiovascular disease." (PMID 33652807, 2021). "Based on apoB, less expensive, simpler, more effective systems to deliver care to prevent and treat cardiovascular disease could be implemented in developing as well as developed countries." (PMID 33598387, 2021). "Both the maternal and fetal elevated TG levels and fetal ApoB levels may be of relevance in the pathogenesis of increased cardiovascular disease in later life for mother and neonate." (PMID 32000699, 2020). "Three large cohort studies also exhibited a consistent outcome that both ApoB and ApoA1 had independent and equal predictive values, and ApoB/A1 ratio was the strongest and most specific indicator for cardiovascular disease that was superior to the cholesterol ratios." (PMID 31123322, 2019). "Because apoB and the apoB/apoA-I ratio have been reported to be better predictors of cardiovascular diseases than traditional lipid measurements, our results provide further evidence that the A → G variant of rs4420638 in the apoC1 gene is associated with cardiovascular disease risk." (PMID 29636060, 2018). "Both ApoB/A1 and TC/HDL-C represent a balance of the anti-atherogenic and atherogenic lipoprotein particles, and are considered better predictors of the future cardiovascular disease risk than the individual lipids." (PMID 29145892, 2017). "Interestingly, the ratio of APOB to APOA1, which is used to assess cardiovascular disease risk, decreased due to weight loss by 8% and remained lower over time (week 52: 7%) for 25 of the 42 study participants." (PMID 28007936, 2016). "Furthermore, the ratios of TG/HDL and apolipoprotein B (ApoB)/apolipoprotein A-1 (ApoA-1) have been shown to be good predictors of MetS and cardiovascular disease." (PMID 25663838, 2015). "Of the metabolic and cardiovascular disease markers high triglyceride concentration (p = 0.02 in men and p = 0.001 in women) and high apolipoprotein B/apolipoprotein A1 ratio (p = 0.04 in men and p = 0.03 in women) were independently associated with low 25OHD level." (PMID 25000408, 2014). "However, patients with extremely low levels of apoB seem to be protected against cardiovascular diseases." (PMID 22496881, 2012). "In addition, weight loss produces a favorable lipid profile such as lowering total – and LDL-cholesterol, apolipoprotein B and triglycerides, and increasing HDL-cholesterol level, thereby decreasing cardiovascular disease risk in these patients." (PMID 19267925, 2009). "Notably, Apoe–/– mice expressing LL37 developed larger atheroma plaques than did control mice, and a positive correlation between plasma LL37 and oxidized phospholipid on apolipoprotein B (OxPL-apoB) levels was observed in individuals with cardiovascular disease." (PMID 38194294, 2024). "Therefore, ApoB may be considered a superior index, compared to LDL-C, for evaluating atherosclerotic cardiovascular risk, particularly in individuals with residual cardiovascular disease risk despite appropriate treatment." (PMID 38393015, 2024). "The significant increase in both LDL/HDL and apoB/apoA during fasting indicated an increased risk of cardiovascular disease due to increase LDL and apoB by autophagy under fasting but reserve or even lowed HDL and apoA which might relate with systematic protection." (PMID 37484967, 2023). "In addition, apolipoprotein B is closely correlated to the occurrence of cardiovascular disease." (PMID 35657779, 2022). "Testing of ApoB levels in childhood or adolescent/young adults and correlating with birth weight may give an indication of whether a persistent ApoB level contributes to the pathogenesis of long-term cardiovascular disease." (PMID 32000699, 2020). "Furthermore, non-HDL cholesterol correlates highly with plasma ApoB levels, now the best parameter to evaluate cardiovascular disease risk." (PMID 25663838, 2015).